IL5 (interleukin 5)
Diseases named in the same sentence as IL5 in open-access papers (continued):
Sharing a sentence is not in itself a finding about the gene and the disease.
tumor (continued). "Immunohistochemical analysis using the monoclonal mouse anti-human IL-5 antibody (R&D Systems, Minneapolis, MN, USA) demonstrated that IL-5 was specifically expressed in tumor cells." (PMID 23420572, 2013). "In fact, we have observed a marked role of IL-5 in promoting intravenous and intrapleural tumor progression via immunomodulatory effects on the host response to tumor." (PMID 20796309, 2010). "Regarding mechanism, IL-33 activates the p38- GATA binding protein 3 (GATA3) signaling pathway to induce M2 polarization of macrophages, promote Th2 cells and ILC2 to secrete tumor-promoting cytokines, mainly IL-4, IL-5, and IL-13, thereby playing a role in promoting tumor development." (PMID 39925809, 2025). "After ICI treatment, CD4+ T cells release interleukin-5 (IL-5), stimulating eosinophil production in the bone marrow, which subsequently leads to their accumulation in peripheral blood and infiltration into tumor tissues." (PMID 39949762, 2025). "Most studies suggest that ILC2s are pro-tumor cells, promoting tumor growth through IL-5." (PMID 40102723, 2025). "Additionally, a positive correlation of Turicibacter with cytotoxic T cells and NK cell populations in the tumor microenvironment as well as serum levels of Eotaxin and IL-5 indicate a treatment-specific change in the gut microbiome." (PMID 39744230, 2025). "In CRC, tumor cells may induce local inflammatory responses, triggering immune cells to secrete IL-5, thereby enhancing the recruitment and activation of eosinophils." (PMID 41239614, 2025). "For example, common-up genes were found to be enriched for metabolic processes, immune-related processes, cell death regulation, and IL-5-mediated signaling pathways, indicating a possible alteration in the metabolic and immune landscape in the tumor microenvironment and the cardiovascular system." (PMID 40270498, 2025). "In addition, Th2 CD4+ T-cells impact the tumor immune microenvironment via the secretion of IL-4, IL-5, IL-13, and IL-17, which exert a pro-tumor growth effect." (PMID 40362529, 2025). "Neutralization of IL-4 and IL-5 results in increased tumor load and impaired clearance." (PMID 39962262, 2025). "In IL-5/CCL11 knockout mice or eosinophil-deficient mice, tumor growth is significantly enhanced." (PMID 40721870, 2025). "Mechanistic studies suggest that Th2‐driven immune responses may enhance eosinophil and macrophage infiltration, promoting IL‐5‐mediated tumor cell cytotoxicity." (PMID 41407509, 2025). "For instance, the generation of IL-13 by ILC2s could contribute to negative outcomes in some cancers, while in others, releasing IL-5 enhances anti-tumor responses." (PMID 40497988, 2025). "We hypothesize that a "cytokine storm" involving tumor-derived G-CSF, granulocyte-macrophage colony-stimulating factor (GM-CSF), IL-5, and IL-6 was responsible for this presentation." (PMID 41431550, 2025). "Furthermore, some natural products can inhibit immunosuppressive factor secretion: IL-10, TGF-β; promote anti-tumor factor secretion: IL-2, IL-5, IL-6, IL-12; reduce immunosuppressive immune cells: Treg, M2 microphage; increase anti-tumor CD8+ T-cells." (PMID 38426097, 2024). "A study indicated that patients with a low baseline concentration of IL-5 in serum specimens or tumor tissues could derive more benefit from ICIs, which was similar to our findings." (PMID 39502692, 2024). "In contrast, interleukins like IL-4, IL-5, IL-10, and IL-13, which contribute to the chronic inflammatory protumorigenic response, promote tumor progression and immune evasion through their interactions with the tumor microenvironment." (PMID 39456897, 2024). "For example, M2 phenotype‐macrophages could secrete IL‐4, IL‐5 and IL‐6 to enhance angiogenesis, immunosuppression and matrix remodelling during tumour progression." (PMID 38680032, 2024). "It has been reported that certain cytokines, such as interleukin-4 (IL-4), IL-5, and IL-13, secreted by Th2 cells could stimulate tumor growth." (PMID 38581008, 2024).
tumor (continued). "Moreover, IL-5 alone correlated positively with B7H4 tumour staining percentage and inversely with TILs score." (PMID 36980202, 2023). "Interestingly, IL-4 expression in the IL-5 KO mice was similar to that of WT mice, but IFN-γ levels were almost three times higher in the IL-5 KO mice, which showed how Th1 suppression favored tumor metastasis." (PMID 37587450, 2023). "IL-5 is a well-known Th2 cytokine and Th2 immunity has been shown to favour tumour growth via promoting angiogenesis and inhibiting anti-tumour immunity." (PMID 36790524, 2023). "Th2 cells release IL-5, IL-4, and IL-13, resulting in tumor cell growth and metastasis." (PMID 36703939, 2023). "Another interesting finding was a positive correlation of IL-5 with B7H4 tumour staining percentage and its negative association with TILs score." (PMID 36980202, 2023). "The source, location, and concentration of expressed IL-33 and IL-5 levels might explain the reason behind its different tumor-related effects." (PMID 37587450, 2023). "On the other hand, one experimental report has suggested that IL-5 may have some tumor-promoting properties, but this was in mice with IL-5 depletion, which would also have diminished eosinophils activity." (PMID 36376448, 2023). "Furthermore, we show that IL-5 provides protection against tumor growth by recruiting and activating eosinophils." (PMID 36376448, 2023). "However, the lactic acid produced by melanoma cells suppresses ILC2 proliferation, survival, and IL-5 production, leading to reduced eosinophil infiltration and increased tumor growth." (PMID 37514187, 2023). "While cytokines like IL-4 and IL-5 are most well recognized for their role in mediating type I immediate hypersensitivity reactions, these cytokines may also influence tumor development." (PMID 37766141, 2023). "IL-5-producing cells expand when treated with IL-25 and more so with IL-33 under Th2-skewing conditions, and IL-5 neutralization impairs eosinophil recruitment and increases tumor lung metastasis." (PMID 37587450, 2023). "In contrast to the previous study, IL-5 was reported to facilitate tumor metastasis." (PMID 35844571, 2022). "Cytokine secretion, such as interleukin-4 (IL-4), IL-5, IL-9, IL-13, and amphiregulin (Areg), by type 2 innate lymphoid cells (ILC2s) is indispensable for homeostasis, remodeling/repairing tissue structure, inflammation, and tumor immunity." (PMID 35592688, 2022). "Furthermore, the IHS influenced T cells in ApcMin/+ mice by increasing the interleukin (IL)-2 and decreasing the IL-5, -6, and -10 levels, thus suppressing tumor development." (PMID 36014805, 2022). "In order to further analyse the immune response induced by T. cruzi treatment, we evaluated the production of IFN-γ (as a readout of a Th1 response) and IL-5 (as Th2-like cytokine) by splenocytes derived from immunised mice after being restimulated with a lysate derived from LL/2 tumour cells." (PMID 36499361, 2022). "In contrast, we observed a significant decrease in IL5, IL10, IL13, and IL6 levels, which are typically associated with tumor-promoting type 2 immune responses, which are known to support tumor growth, metastatic dissemination, and tumor evasion of immune surveillance." (PMID 35715953, 2022). "Additionally, IL-4, IL-5, and IL-13 have been demonstrated to accelerate tumor proliferation and metastasis." (PMID 35546682, 2022). "Genetic overexpression of IL-33 led to increased tumour burden and expression of Il4, Il5 and Il13 in Th2 cells, and this correlated with increased tumorigenesis in the Apcmin/+ mice, while genetic deficiency of IL-33 reduced overall tumour Il4 and Il13 expression." (PMID 36263033, 2022). "Involvement of IL-5-producing ILC2s in antitumorigenic activities was reported using an IL-5 reporter mouse, wherein lung ILC2s were required to retain sufficient number of eosinophils against tumor metastasis, and a blockade of IL-5 signaling resulted in an increased B16F10 metastasis." (PMID 35844571, 2022).
tumor (continued). "Galectin-1 breaks the Th1/2 balance in pancreatic cancer, and the over-expression of galectin-1 in PSC may enhance the release of IL-5, thus, enhancing the tumor fibrosis." (PMID 36428567, 2022). "In addition, also IL-5 has been correlated with anti-tumour activity since is capable of suppressing melanoma growth in the lung by recruiting eosinophils." (PMID 35406451, 2022). "This is supported by the findings from a study that included three groups of mice deficient in C-C motif chemokine ligand 11 (CCL11), both CCL11 and IL-5, and eosinophils, respectively; all the three groups of mice exhibited increased tumor growth in chemically-induced fibrosarcoma." (PMID 35844571, 2022). "However, IL-4 and IL-5 levels were consistently increased in tumour tissue slices compared to tumour-free slices from patient-matched surrounding tissue, with an average fold change of 24.80 and 15.43, respectively." (PMID 35909511, 2022). "Consistently, targeting IL-4 and IL-5 antibodies was reported to suppress tumor progression in multiple cancers, showing targeting Th2 cytokines might be a potential therapy for tumor treatment." (PMID 36564797, 2022). "Interestingly, although the imaging evaluation showed that the tumor lesions increased during pseudoprogression, serum IL-5 and IFN-γ levels inversely decreased and remained below the baseline levels for a long time." (PMID 34239620, 2021). "For example, immunosuppressive ILC2 may release IL-13 to stimulate the development of immunosuppressive myeloid–derived suppressor cells, whereas inflammatory ILC2 produce IL-5 to enhance the cytotoxic activity of eosinophils to suppress tumor progression." (PMID 33427206, 2021). "These newly identified innate IL-5-producing cells thus play a role in tumor surveillance through lung eosinophils and may contribute to development of novel immunotherapies for cancer." (PMID 34239620, 2021). "In this regard, we have detected inflammatory factors including IL-1, IL-6, and TNF-α to help identify whether the increase of IL-5 and IFN-γ levels was caused by tumor progression or the concurrent inflammatory conditions." (PMID 34239620, 2021). "On the other hand, in a mouse model for metastatic lung tumor, systemic administration of IL-33 induced the expansion of IL-5-producing ILC2s, which recruited and sustained eosinophils, critically contributing to increased tumor cell death, and thus preventing metastasis." (PMID 34209038, 2021). "Considering the fine balance of the immune system, transgenic models of eosinophil modulation (such as GATA-1 knockout mice, IL5-/-, or IL5+/+ mice) or spontaneous tumor development would probably be more appropriate for this type of study, as well as the use of avatar mice." (PMID 34572273, 2021). "Also, a great many inflammation-inducing cytokines harbor potent pro-tumor ability, comprised of IL-1β, IL-5 and MCP-1." (PMID 34016791, 2021). "Th2 cytokines such as IL-4, IL-10, IL-5, IL-9, and IL-6 can down-regulate tumor-specific immunity." (PMID 34222249, 2021). "While Th2 and Th17 cells may promote tumor growth through expression of immunosuppressive cytokines including IL-4, IL-5, IL-13, and IL-17A, although the contribution of these cells to the tumor immune landscape is not completely clear." (PMID 34202979, 2021). "Taking into account tumor organization, we hypothesize that increased levels of IL-4 and IL-5 in earlier CRC stages (I-III) could be a result of production by Th2 cells rather than ILC2 cells." (PMID 35008550, 2021).
tumor (continued). "It was also shown that the ILC2 cytokines, IL-5, and GM-CSF could control tumor growth-as genetic ablation of IL-5 and GM-CSF increased the tumor burden in the murine CRC model." (PMID 35008550, 2021). "In addition, more eosinophils infiltrated tumors in CT26 tumor-bearing ∆dblGATA-1 mice injected with IL-33 Eos vs. mice injected with IL-5 Eos." (PMID 32923137, 2020). "It was reported that local IL-33 production could inhibit the tumor growth of a lymphoma cell line, by recruiting eosinophils into tumors through the overproduction of IL-5 from the IL-33-driven ILC2s." (PMID 33233582, 2020). "The expression of IL-5R and the effects of IL-5 were analyzed in human and murine tumor cells." (PMID 32552827, 2020). "In conclusion, high plasma IL-5 at baseline could be a marker for ART-treated KS tumor regression, whereas increased pro-inflammatory cytokine IL-6, and the chemokine IP-10, associate with KS tumor progression." (PMID 32634155, 2020). "It has been recently shown that some human tumor cells from PDAC can produce TSLP leading to increased survival and activation of ILC2s/IL-5/Eosinophil axis which in turn could impair tumor growth by a similar mechanism." (PMID 33233582, 2020). "IL-5 was found to limit B16 melanoma tumor establishment in mice lungs." (PMID 31024531, 2019). "IL-33 EO induced rapid apoptosis of tumor cells with greater efficiency than IL-5 EO." (PMID 31717819, 2019). "Furthermore, time-lapse video microscopy revealed that IL-33-activated EO had higher propensity to migrate towards and interact with tumor cells, in comparison with IL-5 EO." (PMID 31717819, 2019). "IL-4 produced by CD4+ T cells may inhibit angiogenesis, promote the infiltration of eosinophils and macrophages into tumour and exert anti-tumour effects, while IL-5 mainly has immunosuppressive and tumour-promoting function." (PMID 31519961, 2019). "In this model, it was shown that ILC2s mediate antitumor activity either by producing cytokines relevant in tumor control (IL-5, IL-13, and GM-CSF) or by producing CXCR2 ligands (CXCL1 and CXCL2), which could induce the apoptosis of CXCR2+ tumor cells." (PMID 32063901, 2019). "This suggested that eotaxin suppresses tumor growth in the presence of IL-5." (PMID 30477171, 2018). "Furthermore, IL-5, which can be produced by mast cells and eosinophils, has been shown to promote eosinophil infiltration into tumors and suppress tumor metastasis." (PMID 28410235, 2017). "Interestingly, this patient also exhibited an increase over pre-existing baseline tumor-specific IL-5 and IL-10 cytokine responses." (PMID 29258618, 2017). "In the present studies focal irradiation of the tumor reduced the Th2 (IL-4 and IL-5) responses through B cells and inflammation (IL-6, IL-17, GM-CSF, IL-1α), which was accentuated by 2-DG besides removing the systemic immunosuppression through depletion of Tregs." (PMID 25248151, 2014). "After looking at other cytokines not directly associated with tumor progression (e.g., TNFα and IL-5), we observed that the production in untreated MM is almost overlapping with that scored by control PBMC (data not shown)." (PMID 24489445, 2013). "Five mouse-specific cytokines were significantly (P=0.03) higher expressed in VEGFA165 tumours compared with control tumours: interleukin 5 (IL5), IL7, chemokine (C-X-C motif) ligand 9 (CXCL9, MIG), colony-stimulating factor 1 (macrophage) (MCSF) and interferonγ (IFNG)." (PMID 22045186, 2011). "However, eosinophils may also promote tumor progression through their ability to release cytokines and growth factors such as IL-4, IL-5, and vascular endothelial growth factor (VEGF), which can support angiogenesis and tumor evasion." (PMID 40272538, 2025). "Therefore, the rebound of IL-5 levels after an initial dip may support humoral immunity and eosinophil-mediated tumor surveillance—an established favorable prognostic factor in CRC." (PMID 41155334, 2025).
tumor (continued). "However, IL-5 and IL-22 have not been associated with tumor immunotherapy, and their effects still need to be further studied." (PMID 39003253, 2024). "Therefore, the role of IL-5 and eosinophils in tumour development is likely context-dependent and may vary depending on the specific cancer subtype." (PMID 37455828, 2023). "Furthermore, the loss of systemic anti-tumor immunity was associated with the absence of eosinophils at the tumour challenge sites in IL-5−/− mice." (PMID 36790524, 2023). "Moreover, unlike IL-5, IL-13-producing ILC2s had been associated to poor prognosis in breast cancer through immune suppression limiting anti-tumour T cell responses." (PMID 35406451, 2022). "Since CD4+ Th2 cells and Th2 cytokines such as interleukin-4 (IL-4), IL-5, IL-6, IL10 and IL13 were thought to be associated with immunosuppressive contexture and tumor-promoting effects, we believed that LMNB1 could be considered as a biomarker of immunosuppressive microenvironment." (PMID 35241075, 2022). "Additionally, monoclonal antibodies neutralizing IL-5 restored tumour development." (PMID 36261459, 2022). "In addition, neutralizing IL-5 by monoclonal antibodies restored tumor growth." (PMID 34135885, 2021). "Intravenous or intraperitoneal administration of IL-17E (IL-25) in a variety of xenograft tumor models, including breast cancer, showed an antitumoral activity alone or in combination with chemotherapy or immunotherapy due to the induction of eosinophil expansion, through the production of IL-5." (PMID 34572273, 2021). "Interestingly, the frequency of IL-5- and IL-13-expressing ILC2s and IL-17A-producing ILC3s were positively correlated with tumour burden, suggesting that CAC development may be augmented by the local accumulation of these cytokines in the colon." (PMID 33535624, 2021). "However, the increment in IL-5 levels should be regarded positive, since it could contribute to tumour control via eosinophil upregulation." (PMID 33800511, 2021). "Thus, stress-induced production of IL-5 may influence tumor immunity through eosinophilic recruitment into the tumor microenvironment." (PMID 31737559, 2019). "Moreover, Th2 cells' interaction with the TME and particularly with MSCs inhibits immune rejection of the tumor (through the production of Interleukin-4, IL-4, Interleukin-5, IL-5, and Interleukin-13, IL-13) and promotes the presence of immunosuppressive type 2 macrophages." (PMID 28473858, 2017). "Because the age-dependent high levels of IL-10, IL-4 and IL-5 were subsequently decreased by tumor induction only in multiparous mice in the present model, we suggest that parity during fertile life might improve antitumor immunity in aged mouse challenged with tumor-inducing cells." (PMID 28966800, 2017). "Under oxidative stress, M-CSF may produce signals that are cumulative/synergistic with host mediators (e.g., low levels of histamine), facilitating tumor-directed expression of decoy receptors and immune suppressive factors (e.g., dTNFR, IL-5, IL-10, TGF-β, PGE2)." (PMID 24473090, 2014). "Interestingly, α-TEA therapy also resulted in a 2.8-fold increase of IL-5 in the tumor." (PMID 21232138, 2011). "They directly mediate tumor cytotoxicity when cocultured with MH134 cells (an HCC cell line) in the presence of several mediators, such as IL-5 and CCL11." (PMID 40721870, 2025). "Upon release by both tumor and stromal cells, IL-33 activates ILC2s through its receptor, ST2, leading to the production of cytokines such as IL-5 and IL-13." (PMID 40247153, 2025). "For example, studies suggest that tumor-promoting Th2 cells exhibit high levels of IL-10 and TGF-β, whereas Th2 cells with elevated expression of IL-3, IL-5, and IL-13 demonstrate anti-tumor immunity." (PMID 40070825, 2025).